RETN (resistin)
Diseases named in the same sentence as RETN in open-access papers (continued):
Sharing a sentence is not in itself a finding about the gene and the disease.
atherosclerosis (continued). "The development of human calcified aortic stenosis (AS) includes age-dependent processes that have been involved in atherosclerosis, such as infiltration of macrophages in aortic valves, which then promote production of many pro-inflammatory cytokines, including resistin." (PMID 22493735, 2012). "Moreover,resistin is secreted by the macrophages localizing to the atheromas, therebypromoting atherosclerosis in humans." (PMID 19125180, 2008). "However, compared to other adipokines, the specific contribution of resistin to exercise-mediated protective role against atherosclerosis remains incompletely understood, and inter-individual variability in resistin response to exercise interventions adds further complexity to its study." (PMID 40861271, 2025). "Hence, exercise can decrease resistin expression, which may help mitigate the progression of atherosclerosis." (PMID 40861271, 2025). "An Iranian study aimed at determining a potential relationship between psoriasis with subclinical atherosclerosis, where psoriatic patients, in contrast to controls, demonstrated increased carotid intima-media thickness, which was accompanied by increased serum levels of resistin and leptin." (PMID 40095687, 2025). "Thus, the regulation of the interplay between the ECS and resistin could serve as a promising therapeutic strategy to prevent atherosclerosis." (PMID 39050819, 2024). "In addition to modulating insulin sensitivity, resistin plays a role in the development of inflammation and inflammatory diseases (e.g., atherosclerosis and arthritis), regulates carbohydrate and lipid metabolism, and stimulates the proliferation of endothelial cells." (PMID 33924645, 2021). "Therefore, resistin could act as both indicator and initiator of the inflammatory process contributing to the development of various chronic diseases, such as atherosclerosis." (PMID 33651847, 2021). "Therefore, resistin could mediate the inflammatory effects on arterial wall and contribute to the development of atherosclerosis." (PMID 33651847, 2021). "Here, we present data indicating that many atherosclerosis and cardiovascular risk-related proteins that were found to be up-regulated in other Olink studies (e.g., SELE/E-selectin, TNFSF14/LIGHT, VEGFA, RETN/resistin, MMPs) are in fact suppressed by dupilumab in tape-stripped skin lesions." (PMID 32849633, 2020). "Lack of association of resistin with endothelial dysfunction and atherosclerosis might be due to the presence of other more dominant uremia-related toxins leading to increased cardiovascular risks." (PMID 28747175, 2017). "Nevertheless, resistin has primarily been shown to be relevant to inflammation-related diseases like atherosclerosis and arthritis and may have a role in the regulation of pro-inflammatory cytokines’ (IL-6 and TNF-α) expression in human peripheral blood mononuclear cells (PBMC) via NF-κB pathway." (PMID 27608037, 2016). "Resistin has also been shown to have direct effects on endothelial cell activation by inducing the expression of endothelin-1 (ET-1) and the cell adhesion molecules VCAM-1 and ICAM-1, and resistin's secretion by the atherosclerotic macrophages could promote atherosclerosis in humans." (PMID 23484124, 2013). "Thus, the balance of the opposite effects of adiponectin and resistin at the level of the endothelial cell may be an important determinant of endothelial dysfunction, and in turn the progress of atherosclerosis." (PMID 21251282, 2011). "If resistin acts as a proinflammatory molecule, it could be one important link in the intricate interactions between inflammation and dyslipoproteinemia and subsequently atherosclerosis seen in SLE and other inflammatory conditions." (PMID 18234104, 2008). "This review identified CHI3L1, CD36, LEPR, RETN, IL-18, RBP-4, and RARRES2 genes as the potential genetic markers of IR and atherosclerosis in T2DM patients with CAD." (PMID 36984867, 2023).
atherosclerosis (continued). "This review focuses on the link between IR, T2DM, atherosclerosis, CAD, and the potential genetic markers CHI3L1, CD36, LEPR, RETN, IL-18, RBP-4, and RARRES2 genes." (PMID 36984867, 2023). "Adipose tissue-derived factors, known as adipokines (such as adiponectin, leptin, resistin, retinol-binding protein 4 (RBP-4) and visfatin), influence atherosclerosis development and can have either protective or aggravating effects." (PMID 37512134, 2023). "Adipokines from adipose tissue, such as resistin, leptin, adiponectin, and TNF, play a vital role in the inflammation process, which is the main reason for the development of atherosclerosis." (PMID 36299943, 2022). "However, resistin, a proved risk factor for both AD and atherosclerosis, was increased and β-OHB significantly reduced serum level of resistin in ApoE−/− + β-OHB mice, again confirming the possible therapeutic effect of β-OHB in both AD and atherosclerosis via inhibiting lipid-induced inflammations." (PMID 32069870, 2020). "The pro-inflammatory adipokine resistin induces a phenotypic switch of vascular smooth muscle cells (VSMC), a process decisive for atherosclerosis, including morphological changes, increased synthetic activity, proliferation and migration." (PMID 32111889, 2020). "Moreover, some evidence from experimental studies also suggests that resistin may accelerate the pathogenesis of atherosclerosis by promoting endothelial dysfunction, vascular smooth muscle cell proliferation, arterial inflammation, and the formation of foam cells." (PMID 29848323, 2018). "In addition, several studies have suggested that resistin may play a role in atherosclerosis." (PMID 27649254, 2016). "There was slower progression of atherosclerosis (carotid IMT and CAVI) at follow-up in patients with greater reduction of serum resistin and with higher cumulative prednisolone dose." (PMID 27649254, 2016). "We also found slower progression of premature atherosclerosis (evaluated from the carotid IMT and CAVI) in patients with greater reduction of the serum resistin level at follow-up and patients receiving higher cumulative dose of prednisolone." (PMID 27649254, 2016). "Indeed, resistin was found to be more highly expressed in atherosclerotic aneurysms than in normal arteries, while at the same time induces the proliferation and migration of the human vascular smooth muscle cells leading to progression of atherosclerosis in rabbit carotid artery." (PMID 23484124, 2013). "It has been recently suggested that resistin acting through the CAP1 receptor in CKD may increase pro-inflammatory processes and accelerate atherosclerosis in this group of patients." (PMID 37048072, 2023). "However, resistin and RELMβ, the two human homologs of HIMF, have been shown to play critical roles in atherosclerosis." (PMID 34336840, 2021). "Previous studies have shown resistin to participate in various pathological processes including atherosclerosis and cancer progression but not many studies have assessed the role of resistin as a risk factor for all-cause mortality." (PMID 33651847, 2021). "Adipokines released by PVAT include adiponectin, leptin, resistin, visfatin, chemerin, lipocalin-2 (LCN2), fatty acid binding protein (FABP), which show direct evidence of PVAT-derived adipokines have effects on the progression of atherosclerosis." (PMID 30305178, 2018). "PVAT-derived resistin has not been directly shown to influence atherosclerosis, but does increase the expression of osteopontin in VSMCs, which in turn has been implicated in VSMC proliferation and restenosis." (PMID 29467675, 2018). "Furthermore, slower progression of premature atherosclerosis (evaluated by CAVI and carotid IMT) was found in patients with greater reduction of the serum resistin level after a mean follow-up period of three years." (PMID 27649254, 2016).
atherosclerosis (continued). "Lastly, we did not evaluate adipocytokines, such as leptin, adiponectin, resistin, chemerin and visfatin, knowing their relationship with atherosclerosis and angiogenesis." (PMID 26895298, 2016). "Despite some controversy, several studies suggest that resistin plays a central role as a driver of several metabolic pathways, such as angiogenesis, thrombosis, and vascular smooth muscle cell (VSMC) migration and proliferation, all of which contribute to atherosclerosis." (PMID 39184804, 2024). "Actually, no data is available in NGT people about resistin role on atherosclerosis development." (PMID 30832662, 2019). "However, the relationships between circulating levels of novel adipose tissue-derived inflammatory factors, including resistin, vaspin, and visfatin, and the severity of atherosclerosis have not been determined." (PMID 29848323, 2018). "Whether a resistin pathway does exist in humans and, if so, whether it does play a detrimental role on atherosclerosis and clinical outcomes related to IR and LGI is not known." (PMID 28290549, 2017). "Human resistin may play an important regulatory role in the modulation of the interaction between endothelial cells, monocytes/macrophages, and VSMC in the pathogenesis and progression of atherosclerosis, as demonstrated in several experimental, and clinical studies." (PMID 34496965, 2021).
breast cancer (75 papers, 2010 to 2025). A primary or metastatic malignant neoplasm involving the breast. "SAD2 also significantly increased circulating resistin levels, which is associated with more aggressive and metastatic tumors in patients with breast cancer." (PMID 40713647, 2025). "Serum expression levels of leptin, resistin, and visfatin are reliable diagnostic markers of breast cancer and are independent predictive factors of LN invasion and ER-negative breast cancer patients." (PMID 35701840, 2022). "In particular, our group and others have noted that elevated resistin expression is associated with advanced breast tumor characteristics, such as increased tumor stages and lymph node metastasis in breast cancer patients." (PMID 36104403, 2022). "Classic adipokines, such as leptin, adiponectin, and resistin, have been extensively studied in breast cancer and connected with breast cancer risk and progression." (PMID 36077676, 2022). "Resistin is an adipocytokine associated with adverse breast cancer progression; however, its underlying mechanisms in the context of the breast tumor microenvironment remain largely unidentified." (PMID 36104403, 2022). "Enhanced breast cancer cell migration by resistin-stimulated ADSCs was associated with extracellular signal-regulated kinase (ERK) phosphorylation." (PMID 36104403, 2022). "Resistin has been linked with several mechanisms resulting in breast cancer progression, and upregulation of resistin in breast cancer tumors is associated with impaired prognosis." (PMID 34944905, 2021). "In this context, it should be noted that generation and secretion of pro-inflammatory cytokines and adipokines, such as leptin and resistin, is higher in breast-cancer-associated adipocytes than in mature mammary adipocytes." (PMID 34681797, 2021). "In conclusion, our investigation demonstrates an association between RETN gene variants and susceptibility for breast cancer and its progression among Chinese Han women carrying the RETN rs3219175 and rs7408174 polymorphisms." (PMID 32226495, 2020). "This case-control study examined the involvement of four RETN SNPs and clinicopathological features in susceptibility to breast cancer amongst women of Chinese Han ethnicity." (PMID 32226495, 2020). "Higher levels of circulating resistin have been linked to a risk of developing breast cancer, and significantly elevated resistin expression has been documented in patients with breast cancer." (PMID 33313320, 2020). "We investigated possible associations between RETN polymorphisms, clinical and pathological markers, and susceptibility to breast cancer." (PMID 32226495, 2020). "In obese breast-cancer patients, in which adipokines such as leptin and resistin known to be related to obesity and that increase mammary tumor risk, an elevation of FABP4 correlated with tumor size and stage, and with lymph node invasion was found." (PMID 32856199, 2020). "Elevated levels of circulating resistin have been linked to a higher risk of breast cancer, and significantly elevated serum resistin has been documented in patients with breast cancer." (PMID 33313320, 2020). "Meanwhile, other findings indicated that resistin levels were inversely related to breast cancer risk in premenopausal women, supporting a protective role of resistin for these patients." (PMID 33247685, 2020). "We also examined associations between four RETN single nucleotide polymorphisms (SNPs; rs3745367, rs7408174, rs1862513 and rs3219175) and breast cancer susceptibility in 515 patients with breast cancer and 541 healthy women without cancer." (PMID 32226495, 2020). "Our previous study has reported SNP rs3219175 and rs7408174 at greater risk of developing RA disease 44, and the effects of these variants on resistin expression require to be further examined in breast cancer cells in the future." (PMID 32226495, 2020).
breast cancer (continued). "RETN polymorphisms have been identified in various cancers, including colon and lung 16,20,21, but data are scant as to the involvement of RETN polymorphisms in breast cancer." (PMID 32226495, 2020). "Circulating levels of the adipokine resistin increase with adiposity and are associated with higher risk and impaired prognosis of breast cancer." (PMID 32560703, 2020). "High levels of serum resistin and visfatin were found in post-menopausal women with breast cancer, which correlated with tumor size and a high risk of lymph node metastasis." (PMID 31398937, 2019). "Similar to the pancreatic cancer study, another research team found a connection between resistin and relapse-free survival in breast cancer, and resistin associated with more advanced breast cancer." (PMID 30131543, 2018). "Decreased concentrations of adiponectin, and increased concentrations of leptin, IL-6, IL-8, TNF-α, resistin and visfatin were significantly associated with risk of breast cancer." (PMID 29088874, 2017). "Our subgroup analysis suggested that adiponectin, leptin and resistin were associated with incidence of breast cancer in both pre- and postmenopausal women." (PMID 29088874, 2017). "We also found that decreased circulating adiponectin levels and increased leptin, IL-6, IL-8, TNF-α, resistin and visfatin levels are significantly associated with risk of breast cancer." (PMID 29088874, 2017). "Previously published studies have linked elevated levels of serum resistin to higher breast cancer risk and decreased survival in breast cancer patients." (PMID 27314854, 2016). "It should be mentioned that high resistin expression in breast cancer tissue is associated with a more malignant clinic pathological status and poor patient survival." (PMID 27293305, 2016). "As previously noted, high levels of resistin have been linked to risk of breast cancer, particularly in post-menopausal women." (PMID 27314854, 2016). "We provide evidence that resistin expression changes are subtype- and race-specific, but also associated with early stage breast cancer." (PMID 27314854, 2016). "Association of inflammatory cytokines, resistin and IL-6 with breast cancer risk has been reported previously." (PMID 25868978, 2015). "Breast cancer patients show increased resistin concentrations over control, and a recent study indicates that high resistin expression in breast cancer tissue is associated with decreased survival and more malignant characteristics." (PMID 24324792, 2013). "The expression of leptin, adiponectin, and resistin, which represent classic adipokines, and their differential expression in association with clinicopathological parameters have been largely studied in breast cancer." (PMID 36077676, 2022). "Some adipokines expression levels in serum, like resistin, leptin, adiponectin, and visfatin, can serve as risk factors for clinicopathological features of post-menopausal breast cancer, including tumor-node-metastasis (TNM) stage, tumor size, LN metastasis, and histological grade." (PMID 35701840, 2022). "In the present study, we further considered the activation state of patient-derived ADSCs stimulated by resistin, an adipocytokine associated with adverse breast cancer progression, and their impact on breast cancer cell malignancy in the tumor microenvironment." (PMID 36104403, 2022). "Obesity increases systemic levels as well as cellular secretion of many cytokines and adipokines including leptin, IL6, TNFα, IGF1, fatty acid binding protein 4 (FABP4), and resistin, which are all involved in regulating the pathways associated with the development of CSCs in breast cancer tissue." (PMID 36010901, 2022). "Clinically, high levels of resistin in breast cancer tissue have been linked to more advanced tumor stage with large tumor size and lymph node involvement, positive estrogen receptor (ER) status, and poor breast cancer outcome." (PMID 32560703, 2020).